SHH (sonic hedgehog signaling molecule)
Diseases named in the same sentence as SHH in open-access papers (continued):
Sharing a sentence is not in itself a finding about the gene and the disease.
ciliopathies (15 papers, 2019 to 2025). "Based on the findings in ciliopathy mouse models, it has been suggested that ciliary dysfunctions in the inner ear due to the loss of SHH signaling can lead to hearing loss." (PMID 36766700, 2023). "RNA-sequencing on human and mouse trametinib treated cells corroborated these findings with decreased expression of cell cycle, stem cell pathways and SHH-pathway related genes concomitant with increases in genes associated with cell death and ciliopathies." (PMID 37726268, 2023). "An interesting finding in our RNA-seq tumorsphere data was the dysregulation of SHH signaling and enrichment of genes associated with ciliopathies or primary cilia following trametinib treatment." (PMID 37726268, 2023). "The MKS module is critical to ciliogenesis and SHH signaling and is composed of several evolutionarily conserved proteins that are associated with severe ciliopathy phenotypes." (PMID 38292052, 2023). "Our work suggests that dysregulation of SHH signaling is an important consideration for the etiology of hearing loss in ciliopathies." (PMID 33382037, 2020). "Instead, cochlear hypoplasia (shortening) and abnormal tonotopic organization should be considered as a potential etiology for hearing loss in a group of ciliopathies with defective ciliogenesis leading to impaired SHH signaling." (PMID 33382037, 2020). "More generally, our study of the ciliopathy gene mutant Rpgrip1l/Ftm calls for further examination of ciliary and ciliopathy genes in human neurodevelopmental diseases associated with SHH signaling defects." (PMID 30692221, 2019). "In the future, it will be interesting to investigate whether members of the GID complex cause human ciliopathies associated with defects in SHH signal transduction." (PMID 35543155, 2022). "Some clinical features of KCNH1-related phenotypes, as facial and digital malformations, which are included in the phenotype spectrum of some ciliopathies, have been considered as caused by perturbations of signaling pathways, as the SHH, which is involved in morphogenesis processes." (PMID 35639255, 2022). "To test whether rmnd5a morphants develop ciliopathy and/or SHH loss-of-function-related phenotypes, we suppressed the function of Rmnd5a using antisense oligonucleotides (morpholino, rmnd5a-mo)." (PMID 35543155, 2022). "Moreover, an aberrant SHH signaling cause ciliopathies, a disorder in ciliary functions." (PMID 36766700, 2023). "Interestingly, diencephalic hamartomas have been linked to mutations in GLI3 and other SHH pathway genes, suggesting that those observed in ciliopathies could also be caused by defects in SHH signaling." (PMID 30692221, 2019). "Disruption of cilia genes, “ciliopathies,” leads to altered developmental SHH signalling responses and, in severe cases, to forebrain malformations." (PMID 40496915, 2025). "A subset of developmental phenotypes typical for syndromic ciliopathies are due to simultaneously altered SHH signaling." (PMID 35543155, 2022). "All these findings point to a close relationship between the GID complex, SHH signaling, cilia and ciliopathies." (PMID 35543155, 2022). "Importantly, cell migration defects resulting from malfunction of ciliopathy-related molecules have generally been considered a consequence of impaired ability to sense signals, such as SHH, WNT, or PDGF, via primary cilia." (PMID 40632733, 2025). "Although the cause remains unknown, we hypothesize that this severe case of duplicated pituitary gland plus syndrome with thoracoabdominal anomalies may be the result of a ciliopathy leading to elevated SHH expression and axial mesoderm duplication." (PMID 40481881, 2025). "Ciliopathies with skeletal malformations often arise due to defects in genes encoding for the IFT-A and IFT-B components or the dynein motor arms of the primary cilium, leading to defects in ciliary function, including mediating SHH signaling." (PMID 38292052, 2023).
ciliopathies (continued). "Based on comparative analysis of our results and previous studies, we propose that cochlear phenotypes of ciliopathy mutants can be categorized into two groups: a group associated with impaired SHH signaling and the other group without SHH-associated defects." (PMID 33382037, 2020). "Comparative analysis of our results and previous studies suggest that there are two categories of cochlear phenotypes in ciliopathy models: one associated with impaired SHH signaling and the other without SHH-associated defects." (PMID 33382037, 2020). "Furthermore, zebrafish have been used to model human ciliopathies with a craniofacial phenotype and defective SHH signaling." (PMID 32850780, 2020). "Overall, we propose that the GID complex, as an integral part of cilia, is critical for the maintenance of protein homeostasis for several SHH components, and we hypothesize that genes encoding GID complex subunits are novel disease gene candidates for human ciliopathies." (PMID 35543155, 2022). "Here, we show that RPGRIP1L is not required for SHH activation or motoneuron lineage commitment in human spinal progenitors and that this feature is shared by another ciliopathy gene, TMEM67." (PMID 40188187, 2025). "In order to classify other ciliopathies, such as Joubert syndrome (MIM #213300) and Bardet-Biedl syndrome (MIM #209900), the assay needs to be extended with other cilium characteristic parameters, for example SHH signaling or transition zone morphology." (PMID 34040173, 2021).
embryonal tumors (12 papers, 2020 to 2025). "Medulloblastomasare the most common embryonal tumors, classified into four histologic and molecular subtypes based on WNT & SHH." (PMID 41170123, 2025). "Also, the reference samples used in this study may have affected the analytical results, since several subtypes of embryonal tumors rely on congruent pathway activations (e.g. SHH- and WNT-signaling in MB-SHH and MB-WNT, respectively)." (PMID 38158710, 2024). "According to the World Health Organization (WHO) classification of central nervous system (CNS) tumors, this embryonal tumor is divided into a wingless (WNT)-activated, Sonic hedgehog (SHH)-activated, and non-WNT/non-SHH entity." (PMID 33387268, 2021).
Gorlin syndrome (12 papers, 2008 to 2025). "There might be speculation about possible genetic mutation in the activation of SHH pathways, known for the basal cell nevus or Gorlin syndrome, which predisposes patients to the early development of multiple BCCs." (PMID 37240278, 2023). "Background and Clinical Significance: Basal cell nevoid carcinoma syndrome, or Gorlin–Goltz Syndrome (GGS), is a genetic disease caused by germline mutations in genes involved in the Sonic HedgeHog (SHH) signaling pathway, mainly in the PTCH1 gene." (PMID 40729247, 2025). "Patient characteristics for the Gorlin cohort (all genetically diagnosed PTCH1 and SUFU associated Gorlin syndrome patients) vs. the Comparative cohort (all DMB/MBEN, SHH+, <3.5y)." (PMID 34888241, 2021). "Dysregulation of SHH, the most potent and widely expressed HH ligand, is characteristic of basal cell nevus syndrome, also known as Gorlin syndrome." (PMID 33494284, 2021). "Causative mutations in several genes associated with the sonic hedgehog (SHH) signaling pathway, including PTCH1, PTCH2, and SUFU, have been identified in Gorlin syndrome patients." (PMID 29088246, 2017). "Causative mutations in several genes associated with the sonic hedgehog (SHH) signaling pathway, including PTCH1, have been identified in Gorlin syndrome patients." (PMID 29088246, 2017).
liver cancer (11 papers, 2014 to 2025). An epithelial or non-epithelial malignant neoplasm that arises from the liver. "TAMs activate WNT/beta-catenin and SHH pathways, in CSCs, by leading transcriptional activation of stemness related genes in liver cancer, prostate cancer and lymphoma after secreting TNF-alpha, CCL5, pleiotrophin respectively." (PMID 39981232, 2025). "This suggests that Rab23 plays an essential role in liver cancer development and the SHH signaling pathway, which is consistent with our previous studies." (PMID 37884351, 2024). "Application of the JAK2 inhibitor AZD1480 and IL6 neutralizing antibody showed the CD90 and SHH/Gli‐regulated liver cancer stem cell functions were mediated by the IL6/JAK2/STAT3 pathway." (PMID 29722127, 2018). "The stem cell properties of CD90+ liver cancer cells are regulated by the downstream SHH/Gli and IL6/JAK2/STAT3 signalling pathways." (PMID 29722127, 2018). "We also further verified that IL6/JAK2/STAT3 signalling functions downstream of the SHH/Gli pathway in liver cancer stem cells." (PMID 29722127, 2018). "The expression of SOX2 and NANOG, 2 key stem cell biomarkers regulating cell self‐renewal, further verified the role of SHH/Gli signalling in CD90+ liver cancer stem cell regulation in this study." (PMID 29722127, 2018). "Significant alterations of cell proliferation and migration rates, sphere formation and tumorigenicity capacity induced by knockdown or SHH treatment confirmed the function of SHH/Gli signalling in liver cancer stem cell maintenance mediated by CD90." (PMID 29722127, 2018). "Taken together, these results showed that the proliferation, sphere formation and migration capacities of CD90+ liver cancer cells involved activation of IL6/JAK2/STAT3 signalling through the SHH/Gli pathway." (PMID 29722127, 2018). "This study aimed to investigate potential implications of SHH/Gli signalling in CD90+ liver cancer stem cells." (PMID 29722127, 2018). "For further exploration of the involvement of the SHH/Gli axis in liver cancer stem cell activity, CD90+ 97L and Huh7 liver cancer cells were treated with 0.4 g/mL SHH (SRP3156; Sigma‐Aldrich)." (PMID 29722127, 2018). "Inspired by previous reports showing the involvement of SHH signalling in cell proliferation regulation, tumorigenesis and especially liver cancer pathogenesis, we studied the expression of major components of the Shh/Gli signalling pathway in multiple liver cancer cell lines and clinical tissues." (PMID 29722127, 2018). "Additionally, many in vitro studies have found that chronic liver damage or liver cancer may activate the sonic hedgehog (SHH) pathway." (PMID 36548557, 2022). "ALKBH5 amplifies the characteristics of liver cancer stem cells by mediating the expression of SOX4 and activating the SHH signaling pathway, thereby conferring resistance to radiotherapy." (PMID 40823093, 2025). "In liver cancer, MMP-2 and -9 expression and activities were upregulated and downregulated by recombinant N-terminal of Sonic Hedgehog (SHH) and the SHH signaling inhibitor." (PMID 24944688, 2014). "Furthermore, the expression levels of the major SHH pathway proteins Smoothened (SMO) and GLI‐1 were also significantly reduced in shRab23 liver cancer cells compared to the control." (PMID 37884351, 2024). "Correlation of the expression of SHH signalling components and CD90 in liver cancer cells and clinical tissues, as well as in enriched CD90+ liver cancer stem cells and the TCGA database, were analysed by quantitative RT‐PCR, Western blotting and flow cytometry." (PMID 29722127, 2018).
microphthalmia (10 papers, 2009 to 2024). Congenital or developmental anomaly in which the eyeballs are abnormally small. "Mutations affecting the SHH pathway have been associated with milder ocular developmental anomalies including microcornea, microphthalmia, coloboma, and malposition of the optic nerve." (PMID 32852652, 2021). "PAX2 malformations have been associated with optic nerve coloboma, SIX6 mutations with bilateral anophthalmia and pituitary abnormalities as well as microphthalmia, CHX10 mutations with microphthalmia, and SHH mutations with human microphthalmia and coloboma." (PMID 19158959, 2009). "Previous research has linked mutations in genes such as CHX10, MAF, PAX6, PAX2, RX (RAX), SHH, SIX3, OTX2, and SOX2 to phenotypes associated with microphthalmia, anophthalmia, and coloboma (MAC)." (PMID 39129019, 2024). "Ultimately, consistent with its role as a SHH signaling mediator and similar to the mouse mutant phenotype, a human VAX1 mutation has been found in a patient with microphthalmia in association with cleft lip/palate." (PMID 30073412, 2019). "Occasionally, mutations in SHH have been reported in milder, isolated ODA cases presenting microphthalmia and/or coloboma." (PMID 30073412, 2019). "SHH is associated with three distinct disorders: holoprosencephaly 3 (HPE3, OMIM #142945), single median maxillary central incisor (SMMCI, OMIM #147250) and microphthalmia with coloboma 5 (OMIM #611638)." (PMID 38884091, 2024). "At the mild end of the disease spectrum, SHH mutations have resulted in more subtle effects on specific eye components, such as isolated iris and uveal-retinal coloboma, with or without microphthalmia." (PMID 35749127, 2022).
polydactyly (9 papers, 2014 to 2023). A disease characterized by the presence of polydactyly, including syndromic and non-syndromic forms. "Previous studies have shown that the vast majority of polydactylies are associated with Sonic Hedgehog (SHH) signaling pathway and ciliogenesis process." (PMID 32228435, 2020). "The current genetic and molecular classification suggest that at least six different types of polydactylies are caused by mutations in two different genes, i.e., SHH enhancer ZRS and the GLI3, causing PPD1, PPD2, TPT-PS, PPD4, PAPA1, and Haas type." (PMID 30459804, 2018). "We previously reported that a novel mutation in the ZRS resulted in preaxial polydactyly (PPD) type I by inducing ectopic expression of SHH, and we further identified hnRNPK as a mediator that enhanced the interactions between mutant ZRS and the SHH promoter in vitro." (PMID 37608075, 2023). "The disruption or mis-regulation of SHH pathway often results in congenital birth defects, such as holoprosencephaly and polydactyly." (PMID 32228435, 2020). "Accordingly, differences in SHH levels, between Silkie and RA-induced polydactylies, could account for the observed discrepancies in muscle numbers." (PMID 37215090, 2023). "We speculate that the SNPs close to or in RNF32 may be critical for regulating the temporal and spatial expression of SHH, which contributes to polydactyly in Houdans." (PMID 26859147, 2016).
lung adenocarcinoma (8 papers, 2016 to 2025). A carcinoma that arises from the lung and is characterized by the presence of malignant glandular epithelial cells. "The results revealed that the expression rate of SHH protein exhibited a substantial increase in lung adenocarcinoma tissues with EGFR gene mutations (P = 0.012; 83.8%)." (PMID 39721017, 2025). "Our study is the first to demonstrate that activation of the SHh/Gli pathway is associated with changes in expression of EMT markers in lung adenocarcinoma." (PMID 27533453, 2016). "In addition, we conducted IHC staining on 108 lung adenocarcinoma tissues and assessed the association between the protein levels of SHH, DUSP13B, p‐STAT3, and EGFR gene mutation status." (PMID 39721017, 2025). "Surprisingly, the mRNA levels of SHH and GLI1 were markedly upregulated in lung adenocarcinoma tissues with EGFR mutations (P < 0.0001 and P = 0.048, respectively)." (PMID 39721017, 2025). "We also analyzed the association between SHH, DUSP13B, and p‐STAT3 proteins in lung adenocarcinoma tissues and found that p‐STAT3 was significantly positively correlated with SHH but negatively correlated with DUSP13B." (PMID 39721017, 2025). "Our experiments revealed that SH regulated the Hedgehog signaling pathway in lung adenocarcinoma by downregulating the protein levels of the Hedgehog pathway nuclear transcription factor Gli1 and the Hedgehog pathway key factors SHh, Ptc, and Smo." (PMID 41444284, 2025). "Our results demonstrate that inhibition of SHh/Gli signaling have the capability to restore E-Cadherin expression both in vitro and in vivo, indicating that SHh/Gli signaling regulates EMT in lung adenocarcinoma through suppression of E-Cadherin." (PMID 27533453, 2016). "Our results strongly suggest that SHh/Gli signaling promotes cell migration and invasion in lung adenocarcinoma and that inhibitors of this pathway that target Gli or Smo significantly suppress this invasion in vitro." (PMID 27533453, 2016). "The molecular mechanism how the SHh pathway regulates EMT in lung adenocarcinoma remains to be further explored." (PMID 27533453, 2016). "The association among expression of SHH, DUSP13B, and p‐STAT3 proteins in lung adenocarcinoma." (PMID 39721017, 2025). "To elucidate whether SHh/Gli signaling enhances cell migration, we carried out a wound-healing assay in two lung adenocarcinoma cell lines A549 and H1666." (PMID 27533453, 2016). "We then utilized the GEPIA2 online platform to examine the correlation among the mRNA levels of SHH, GLI1, DUSP13B, and STAT3 in lung adenocarcinoma tissues from the TCGA dataset." (PMID 39721017, 2025). "In lung adenocarcinoma, p‐STAT3 is positively correlated with SHH but negatively correlated with DUSP13B." (PMID 39721017, 2025). "The relationship of SHh pathway to EMT has not been previously studied in lung adenocarcinomas and the existing data from other solid tumors is controversial." (PMID 27533453, 2016).
microcephaly (8 papers, 2018 to 2024). A congenital or acquired developmental disorder in which the circumference of the head is smaller than normal for the person's age and sex. "The probands' SHH alterations were carried by 72 relatives, who were weakly symptomatic (13%, with microcephaly, intellectual deficiency or hypotelorism) or asymptomatic (37%)." (PMID 38558491, 2024). "In Xenopus laevis embryos, injection of HMGN1 protein causes body axis curvature, cyclopia and microcephaly, which are all phenotypes associated with aberrant SHH signaling." (PMID 36995257, 2023). "Even in human malformation syndromes, increased activity of the SHH pathway is thought to be associated with macrocephaly (large brain), and decreased activity is associated with microcephaly (small brain)." (PMID 34884862, 2021). "This gene plays an important role in microcephaly, developmental delay, short stature, and facial dysmorphism by stimulating the SHH pathway." (PMID 38473071, 2024).